CCR1 (C-C motif chemokine receptor 1)
Diseases named in the same sentence as CCR1 in open-access papers (continued):
Sharing a sentence is not in itself a finding about the gene and the disease.
breast cancer (continued). "In this study, the transcriptional regulatory mechanism of the human CCR1 gene was investigated using MDA-MB-231 breast cancer cells." (PMID 29212252, 2017). "Next, to investigate the paracrine mechanism that cancer cell CCL5 operates to promote angiogenesis, we orthotopically implanted breast cancer cells into mice, which were homozygous null for either CCR1 or CCR5." (PMID 27863423, 2016). "Thus, the reciprocal expression pattern of CCL5 and specifically CCR1 suggests a predominant chemokine/receptor interaction between CCL5-producing ASCs and CCR1-expressing basal breast cancer cells in the 3D co-spheroids." (PMID 37444610, 2023). "Further, inhibition of CCL3-CCR1 (CC-chemokine receptor-1) axis using anti-CCL3 antibody or deletion of CCL3/CCR1 could effectively reduce breast cancer lung metastasis." (PMID 38037106, 2023). "Future investigations, e.g., using gene silencing, may further validate the impact of the CCL5/CCR1 interaction on breast cancer progression in a 3D adipose microenvironment." (PMID 37444610, 2023). "CCR1 functionality for migration of basal breast cancer cells was proven." (PMID 37444610, 2023). "CCR1, 3 and 5 are known as the receptors of CCL5, and we then evaluated them in breast carcinoma tissues and examined the association between CCL5 immunoreactivity in stromal cells and clinicopathological factors according to the status of CCR1, 3 and 5 in carcinoma cells." (PMID 33671956, 2021). "Both ACKR2 and CCR1 have been shown to be important in the progression of breast cancer; therefore, understanding early interactions between these receptors could reveal key insights, which drive later pathology." (PMID 32467242, 2020). "CCL2-induced chemokine cascade in macrophages contributes to the metastasis of breast cancer, and CCR1 inhibition may be utilised to treat metastatic disease." (PMID 29685151, 2018). "The steady-state levels of CCR1 mRNA were examined in various breast cancer cell lines." (PMID 29212252, 2017). "Similarly, the knock-down of CCR1 was experimentally shown to inhibit metastasis of breast cancer." (PMID 35758822, 2022). "We further examined whether CCL5 and CCR1, 3 and 5 served as prognostic factors in breast cancers." (PMID 33671956, 2021). "However, it remains largely unknown whether CCR1 is overexpressed in breast cancer tissues, and whether CCR1 promotes breast metastasis." (PMID 29212252, 2017). "However, the functional role of CCR1 is unclear in breast cancer metastasis." (PMID 29212252, 2017). "A number of GPCRs have been previously reported to be overexpressed in breast cancer, including CCR1, Opsin-3, CXCR4, PAR1, PAR2, EP2, EP4, GPR30 and the C3A anaphylatoxin chemotactic receptor, although whether any of these are regulated by RGS2 remains unknown." (PMID 18067675, 2007). "In breast cancer patients, levels of CCL23 and CCR1 expression correlated with metastasis and decreased survival; however, HER2-positive breast cancer cases corresponded with low levels of CCL23/CCR1 expression and better prognosis." (PMID 37185750, 2023). "Genetic deletion of CCL3 or CCR1 prevented pulmonary metastasis in the PyMT breast cancer murine model and thus it was concluded that the CCL3/CCR1 axis activated in macrophages is responsible for metastatic seeding of the lung." (PMID 36982211, 2023). "As a proof-of-concept, the adipocyte/breast cancer spheroid model was used to analyze the expression of CCL5 and CCR1 complementary to the ASC co-spheroid model." (PMID 37444610, 2023). "CCL16 binds to chemokine receptors (CCR1, CCR5, and CCR8) to activate angiogenesis in vascular endothelium and is related with prognosis in breast cancer and lung cancer." (PMID 36245978, 2022). "On the other hand, the immunoreactivity of CCR1, CCR3 and CCR5 were observed in the cytoplasm of breast carcinoma cells." (PMID 33671956, 2021).
breast cancer (continued). "In line with this notion, the combined treatment with a CCR1 antagonist and anti-PDL1 antibody significantly reduces tumor burden compared to either of single treatments in a mouse model of breast cancer." (PMID 30483271, 2018). "In the mammary tumors developed in mice, CXCL5 (a CXCR2 ligand) and CCL5 (a ligand for CCR1/3/5) can promote infiltration of MDSCs and Treg cells respectively, although their roles at metastatic sites remain to be identified." (PMID 26275794, 2015). "Co-culturing also lead to changes in gene expression in the breast cancer cells, which upregulated a shared receptor for CCL2 and CCL7, the chemokine receptor CCR1 upon co-culturing with tumor-supportive fibroblasts." (PMID 24068959, 2013). "We therefore tested whether CCR1 expression by cancer cells was critical for some of the tumor supportive functions of fibroblasts by stably expressing shRNAs targeting CCR1 in Cal51 breast cancer cell line (knockdown efficiency was quantified by both qRT-PCR and immunoblotting)." (PMID 24068959, 2013). "CCR1 is the C-C motif chemokine receptor ligand 5 (CCL5) and has been reported to be a chemokine that fosters metastasis and is expressed during crosstalk between breast cancer and stromal cells." (PMID 38920683, 2024). "Thus, the context-dependent expression of the CCL5/CCR1 axis shown in the 3D co-spheroids may act as a tumor-promoting factor when tumor cells and mammary fat cells come into close contact in a 3D environment, as is the case with the infiltration of breast cancer cells in adjacent adipose tissue." (PMID 37444610, 2023). "The combination of the CCR1 antagonist CCX9588 with an anti-PD-L1 antibody has shown promise as a therapeutic approach, synergistically inhibiting primary tumor growth and lung metastasis in an in situ breast cancer mouse model." (PMID 38274805, 2023). "Besides, HECTD3, PSMB10, UBD, UBE2C, and UBE2S involved in the ubiquitin proteasome pathway, as well as CCL2, CCR1, CXCL10, CXCL11, and IL2RG implicated in the cytokine–cytokine receptor interaction pathway, might be used for evaluating the efficacy of neoadjuvant chemotherapy in breast cancer." (PMID 29685151, 2018). "Silencing of AKT1 in T24 bladder carcinoma cells and Capan-1 pancreatic carcinoma cells yielded similar results, suggesting that CCR1 expression activation via the AKT-STAT3 pathway is not restricted to breast cancer cells." (PMID 29212252, 2017). "RT-PCR analysis showed that CCR1 mRNA levels were readily detectable in most tested breast cancer cell lines, but not in untransformed MCF12A breast epithelial cells." (PMID 29212252, 2017). "Notably, it has been reported that activation of the CCL2–CCR2 axis prompts TAM to secrete another chemokine CCL3, which in turn activates its receptor CCR1 in TAM and promotes lung metastatic seeding in a breast cancer mouse model." (PMID 27136535, 2016). "Thus, also using the established co-spheroids composed of adipocytes and breast cancer cells, the expression of tumor-promoting factors (CCL5/CCR1) depending on the type of breast cancer cell could be demonstrated in a 3D environment." (PMID 37444610, 2023). "The upregulation of CCR1 and CXCR6 and the downregulation of CXCR6 ligand (CXCL16) in cells other than MB-231, suggest that alternative chemokine-related axes may be involved in the trafficking of breast cancer cells to the bone marrow." (PMID 35158871, 2022). "From these findings, we speculated that CCL5 might promote breast cancer progression via CCR3 but not CCR1 or CCR5." (PMID 33671956, 2021). "In summary, we immunolocalized CCL5 and CCR1, 3 and 5 in breast carcinoma tissues and demonstrated that the expression of CCL5 in stromal cells was significantly correlated with tumor progression in a paracrine manner via CCR3 expressed in breast carcinoma cells." (PMID 33671956, 2021).
breast cancer (continued). "Therefore, CCL2, CCR1, CXCL10, CXCL11, and IL2RG might be involved in neoadjuvant chemotherapy in breast cancer via the cytokine–cytokine receptor interaction pathway." (PMID 29685151, 2018). "Actually, the risk of recurrence was significantly higher in patients with breast carcinomas positive for CCL5 and CCR3 but negative for CCR1 and CCR5." (PMID 33671956, 2021). "CCL5 and CCR5 (but not CCR1 and CCR3) are overexpressed in the basal and HER-2+ breast cancer subtypes." (PMID 29216863, 2017). "Furthermore, the risk of recurrence was significantly higher in the patients with breast carcinomas positive for CCL5 and CCR3 but negative for CCR1 and CCR5, as compared with other patients." (PMID 33671956, 2021).
rheumatoid arthritis (27 papers, 2011 to 2025). A chronic, systemic autoimmune disorder characterized by inflammation in the synovial membranes and articular surfaces. "One example is rheumatoid arthritis, where CCR1 is also associated with pathology." (PMID 32467242, 2020). "The CCR1 inhibitor CP-481715 can improve inflammation by reducing the number of monocytes in synovial effusions in patients with rheumatoid arthritis." (PMID 38730482, 2024). "Although CCR1 has been recognized as a crucial target in rheumatoid arthritis (RA) treatment, its role in osteoarthritis remains inadequately explored." (PMID 38831316, 2024). "The available experimental studies indicate that CCR1 is involved in the pathogenesis of diseases with large neuroimmunological components, such as rheumatoid arthritis, disc inflammation, multiple sclerosis, and diabetes." (PMID 37570736, 2023). "Many CCR1 antagonists have failed or provided minimal results during clinical trials for a wide variety of diseases from multiple sclerosis and rheumatoid arthritis to neuropathic pain and allergic contact dermatitis." (PMID 35399952, 2022). "CCX354-C and BMS-817399 are antagonists of CCR1 and have entered clinical trials for the treatment of rheumatoid arthritis." (PMID 35887379, 2022). "In rheumatoid arthritis, CCR1 regulates the expression of TNFα and IL-10, and is therefore an efficient therapeutic target." (PMID 33509198, 2021). "CCR1 promotes monocytic tissue infiltration and plays a major role in various other disease processes, including autoimmune diseases like rheumatoid arthritis." (PMID 32963283, 2020). "CCR1 inhibitors have already entered clinical trials for the treatment of autoimmune diseases such as rheumatoid arthritis and so have the potential to be tested in a lung cancer setting." (PMID 26183450, 2015). "Genes showing lower levels of expression in AD included ICAM-1, IL-1B, CCR1, IFIH1, SOCS1, TNFAIP3 and TNFSF13B, which are strongly associated with acute and chronic inflammation and adult rheumatoid arthritis." (PMID 26310571, 2015). "Treatment of rheumatoid arthritis patients with a CCR1 inhibitor has been shown to reduce leukocyte numbers in synovial tissue." (PMID 25170619, 2014). "CCR1 antagonism has been seen as a potential strategy for diseases such as rheumatoid arthritis and multiple sclerosis; however, clinical trials for the antagonists developed have generally failed in phase 2 after being found safe, but not efficacious for treatment." (PMID 30279500, 2018). "Furthermore, recent clinical trial data demonstrate efficacy of CCR1 inhibition in rheumatoid arthritis, including reductions in pain." (PMID 25170619, 2014). "Also, its cognate receptor (CCR1) has been shown to be upregulated in synovial tissue of patients with rheumatoid arthritis." (PMID 24455421, 2013). "Studies have demonstrated that blocking CCR1 can inhibit macrophage infiltration in the synovium of knee joints in rheumatoid arthritis (RA) patients." (PMID 38831316, 2024). "CCL7 is also significantly upregulated in rheumatoid arthritis, activating the JAK2–STAT1 pathway through CCR1 to form an autocrine feedback loop." (PMID 41430036, 2025). "Antibodies against CCR1, CCR2, and CCR5 have been developed for the treatment of rheumatoid arthritis." (PMID 37760825, 2023). "Earlier, we reported the up-regulation of CCR1 and CCR2 in PB B cells activated in vitro and in circulating B and T lymphocytes in patients with rheumatoid arthritis." (PMID 32708233, 2020). "Importantly, several CCR1 antagonists, such as MLN3897 for rheumatoid arthritis, BX471 for multiple sclerosis, and BAY86-5047 for endometriosis, are under investigation in clinical studies." (PMID 38612597, 2024). "Importantly, several CCR1 antagonists have entered clinical trials, including MLN3897 and CP-481,715 for rheumatoid arthritis, BX471 for multiple sclerosis, AZD-4818 for chronic obstructive pulmonary disease, and BAY86-5047 for endometriosis." (PMID 37570736, 2023).
rheumatoid arthritis (continued). "The aim of this study was to provide more insight into the question as to why blockade of CCR1, CCR2, and CCR5 may have failed in clinical trials in rheumatoid arthritis (RA) patients, using an in vitro monocyte migration system model." (PMID 21747955, 2011). "The oral CCR1 inhibitor, CCX354-C, was investigated in a phase 2 RTC of rheumatoid arthritis and was tolerable and safe but failed to yield clinical benefit." (PMID 38899167, 2024).
atherosclerosis (26 papers, 2011 to 2026). A disease characterized by the build-up of fatty material and calcium deposition in the arterial wall resulting in partial or complete occlusion of the arterial lumen. "Mice deficient for CCR5 show reduced atherosclerosis development upon high fat diet feeding, although CCR1-deficient mice show clearly increased plaque development." (PMID 26175090, 2015). "In light of our data here, we speculate that the accelerated atherosclerosis seen in the CCR1 deficient mice may be due to the selective loss of CCR1:CXCL4 signalling in macrophages within plaques that normally would lead to lower modified LDL uptake." (PMID 29930254, 2018). "However, the role of CCL3 in atherosclerosis may be dependent on the various receptors as deficiency of CCR1 in ApoE−/− mice fed a WD for 10 to 12 weeks led to accelerated atherosclerosis and greater plaque size and infiltration of T lymphocytes." (PMID 33503867, 2021). "ITGAX and CCR1 were identified as potential biomarkers for atherosclerosis, while macrophage-related genes, including ITGAX/CD11c and interferon regulatory factor 5, are strongly associated with symptomatic carotid artery disease." (PMID 39845786, 2024). "To provide targeted diagnostic assistance for atherosclerosis patients, we constructed a proprietary Nomogram model based on the expression of PLEK, IRF8, BTK, CCR1, and CD68." (PMID 38716195, 2024). "The use of monocyte CCR1 in arterial recruitment is due in part to activated chemokines of platelet deposition, which is important in the early stages of atherosclerosis." (PMID 36061537, 2022). "The immune-associated genes in both atherosclerosis and osteoporosis from WGCNA mainly included TREM1, CYBB, CCR1, CD83, CD52, IL7R, and THBS1." (PMID 35937806, 2022). "While CCR5 showed a protective role in atherosclerosis by a mechanism involving interleukin-10, CCR1 supported inflammation and neointima formation after vascular injury." (PMID 30006564, 2018). "The expression of RANTES receptors, CCR1 and CCR5, on various cell types implicated in atherosclerosis further illustrates their role in this disease." (PMID 29038476, 2017). "Another possible explanation for this differential involvement of CCR1 and CCR5 in atherosclerosis is the contrary effects on the Th1/Th2 balance, with CCR1 deletion favoring a proatherogenic Th1 response." (PMID 26175090, 2015). "CCR5−/− mice are protected against atherosclerosis while CCR1−/− mice have accelerated lesion formation." (PMID 22359597, 2012). "To further investigate the potential role of gut microbiota-associated core macrophage genes in atherosclerosis, we applied unsupervised clustering methods based on the expression of PLEK, IRF8, BTK, CCR1, and CD68 to classify atherosclerosis patients into groups A and B." (PMID 38716195, 2024). "Gut microbiota-associated macrophage genes (PLEK, IRF8, CD68, CCR1, and BTK) may be implicated in the pathogenesis of atherosclerotic plaques and could serve as diagnostic markers to aid patients with atherosclerosis." (PMID 38716195, 2024). "However, CCR1 and CCR5 appear to exhibit opposing effects, as CCR1 seems to be anti-atherosclerotic in the context of T cell recruitment in murine atherosclerosis, whereas CCR5 rather has a pro-atherogenic role (section The Classic: Monocytes)." (PMID 35087886, 2021). "If we extrapolate our findings here that CCR1 is a bona fide receptor for CXCL4 on monocytes, then our findings may explain at a mechanistic level why deletion of CCR1 in mice has been shown to enhance atherosclerosis in two independent studies." (PMID 29930254, 2018). "Since accelerated atherosclerosis and increased mortality is often observed in arthritic patients (reviewed in43), blockade of CCR1 may be detrimental." (PMID 29930254, 2018).
atherosclerosis (continued). "Notably, CCR1- but not CCR5-deficiency seems to protect only from early atherosclerosis in Apoe–/– mice on a WD for 4 weeks, suggesting temporal differences in CCR-dependent leukocyte recruitment." (PMID 33681219, 2021). "Assuming the in vitro data described here extrapolates to the clinical setting, then it would strongly argue against targeting CCR1 in atherosclerosis and may point to unforeseen side effects following the long-term use of such molecules for the treatment of other inflammatory disorders." (PMID 29930254, 2018). "Thus, CCR1 may be protecting from atherosclerosis by preventing excessive T cell and monocyte influx into atherosclerotic vascular wall." (PMID 24741577, 2014). "Leveraging machine learning algorithms, we have identified PLEK, IRF8, BTK, CCR1, and CD68 as evaluative markers to assist in the diagnosis of atherosclerosis." (PMID 38716195, 2024). "Platelets express some functional chemokine receptors such as CCR1, 3, 4, and CXCR4, which are involved in infection, hemostasis, inflammation, and even in the development of atherosclerosis." (PMID 34425822, 2021). "Surprisingly, looking at the role of CCR1 and CCR5 in general atherosclerosis development, their role appears to be contradicting." (PMID 26175090, 2015). "Additionally, platelets express some functional chemokine receptors such as CCR1, 3, 4, and CXCR4, which are involved in infection, hemostasis, inflammation, and even in the development of atherosclerosis." (PMID 34425822, 2021). "Future studies should clarify whether CCR1 and CCR2, in addition to CCR5, could contribute to the beneficial effects of direct CCL4 inhibition on atherosclerosis." (PMID 32911750, 2020). "Apart from CCR5 and CCR1, CCR3 has been shown to be overexpressed in CD68+ macrophage rich areas of human atherosclerotic lesions, however there is not sufficient information regarding its roles in atherosclerosis, especially through interaction with CCL5." (PMID 33503867, 2021).